CD99 (CD99 molecule (Xg blood group))
Diseases named in the same sentence as CD99 in open-access papers (continued):
Sharing a sentence is not in itself a finding about the gene and the disease.
tumor (continued). "Distinct from T-ALL cells, the other tumor cells did not kill each other and still proliferated normally, although they have high expression of CD99 or CD7, the CAR-targeting antigen." (PMID 37112766, 2023). "Our results prove the validity of CD99 in PCNSL, and it may serve as a potential target to inhibit the proliferation and migration of tumor cells at this stage." (PMID 37120690, 2023). "CD99 CAR transducing shCD99 MOLT-4 cell lost the attacking target and prolificated normally, which demonstrated that T-ALL cells still retain the immunocompetence to attack tumor cells, as do normal T cells." (PMID 37112766, 2023). "In addition, anti‐CD99 CAR‐T cells can specifically recognize CD99 antigen on tumor cells, and effectively inhibit the proliferation and induce apoptosis of tumor cells." (PMID 37021816, 2023). "Immunohistochemically, the tumor cells were positive for CD117, vimentin, CD56 and NSE and focally expressed desmin; the cells were negative for myogenin, S-100, SYN, INSM1, CD34, STAT6, INI-1, Brachyury, ERG, TLE1, AE1/AE3, WT-1, CD99 and SMA." (PMID 35488288, 2022). "The tumor was positive for CD117, Vim, CD56 and NSE and showed focal expression of desmin but was negative for myogenin, S-100, SYN, INSM1, CD34, STAT6, INI-1, Brachyury, ERG, TLE1, AE1/AE3, WT-1, CD99 and SMA." (PMID 35488288, 2022). "Immunohistochemically, the tumor cells were positive for CD99 and NKX2.2, and negative for CD45, CK (AE1/AE3), S100 protein, myogenin, MyoD1, and WT-1." (PMID 36451511, 2022). "Immunohistochemistry showed that the tumor cells were focally positive for CD99 and BCL-2 and negative for CD34, S100, desmin, and myogenin." (PMID 35797605, 2022). "Immunohistochemical staining showed that the tumor cells were positive for vimentin and Bcl-2 but negative for S-100, desmin Syn, WT-1, EMA, CD34, and CD99; the Ki-67 index in tumor cells was 40%." (PMID 36482604, 2022). "Histologically, a cellular tumor comprising malignant oval to spindle cells with necrosis was observed, which was positive for Bcl-2, CD99, and FLI-1, but negative for pan-cytokeratin, STAT6, and CD34." (PMID 36033527, 2022). "All cases of EWS exhibited CD99 expression, with the exception of 2 cases in which a heterogeneous immunostaining as well as a non-specific focal staining of tumor stroma was observed." (PMID 34943491, 2021). "In immunohistochemical analysis, tumor cells were stained for CD34, CD99, and Bcl2." (PMID 33567630, 2021). "The documented pro- and anti-tumour activity of CD99 is mirrored by both positive and negative roles for CDC42 in tumour progression." (PMID 34374417, 2021). "On immunohistochemistry, the tumor cells had typically strong and diffuse positivity for vimentin and BCL2, focal positivity for CD34, and weak diffuse positivity for CD99 but negativity for cytokeratins AE1–AE3, actin HHF35, actin 1A4, calponin, caldesmon, desmin, S-100 protein, and collagen IV." (PMID 34211794, 2021). "We observed that our anti-CD99 CAR T cells showed robust cytotoxicity specifically against CD99+ T-ALL cell lines and primary tumor cells in vitro and significantly prolonged cell line-derived xenografts (CDXs) or patient-derived xenografts (PDXs) models survival in vivo." (PMID 34627328, 2021). "Adhesion of leucocytes to the EC is CD99 independent, whereas for MDA-MB-231 tumour cells, both blocking antibodies and RNAi-mediated CD99 depletion significantly reduced tumour-EC adhesion." (PMID 34374417, 2021). "Histopathology of the tumors and expression of tumor markers CD99, SPARC, and MyoD1 did not change significantly upon successive mouse‐to‐mouse passaging in 12 PDX models studied by IHC." (PMID 33837665, 2021). "Expression studies reveal that CD99 has both positive and negative effects on human tumour progression, depending on the tumour type." (PMID 34374417, 2021).
tumor (continued). "Notably, the expression of WT1 and cyclin D1 was also retained in those cases in which the conventional tumor markers (myogenin, desmin and MyoD1 for RMS; CD99 for EWS; NB84 for NB) were focally expressed or more rarely absent." (PMID 34943491, 2021). "CD99 acts as an upstream regulator of the PTPN12-mediated negative feedback loop for regulating ligand-induced dimerization or oligomerization of plasma membrane protein kinases, which are involved in tumor development and progression." (PMID 33050232, 2020). "Immunohistochemical staining revealed that the tumor cells were positive for CD34, CD99, and BCL2." (PMID 32638177, 2020). "Negative tumour regulators like CD99, and biomarkers whose decreased expression has been correlated with other tumours, like PGMRC1 were identified with consistently decreased expression and excretion levels, too." (PMID 31900160, 2020). "Immunobiologically, the tumor diffusely expressed estrogen receptor (ER), progesterone receptor (PR), AE1/AE3, desmin, Wilm’s tumor-1 (WT-1), CD56, and CD99." (PMID 32921307, 2020). "We present a series of 15 cases of molecularly confirmed ES, trying to find the meaning of its immunoreactivity for CD99 and PAX8, to determine whether there is enough sensitivity to be useful in the diagnosis of these tumours." (PMID 32675940, 2020). "Therefore, the heterogeneity of scoring for CD99, BCL11B, and GLG1 in different cores per sample, originating from different regions of a given tumor block, was assessed." (PMID 32164354, 2020). "For CD99, 81% of non-EwS tumor samples were classified consistently across all three cores per sample, for BCL11B 97.6%, and for GLG1 and 94.8%, indicating only little intra-tumoral heterogeneity in EwS differential diagnoses." (PMID 32164354, 2020). "Immuno-stains with adequate controls showed the tumor cells to be positive for CD99 and bcl2, but negative for CD56, TTF1, S100 and CD57." (PMID 31377551, 2019). "Tumour cells showed diffuse CD99 immunoreactivity and negative staining for epithelial membrane antigen, STAT6 and glial fibrillary acid protein." (PMID 30819134, 2019). "Immunohistochemical analysis showed that the tumour was positive for vimentin, CD99, Bcl-2 and CD34 and negative for D2–40, desmin, S-100, SMA and CK and the Ki-67 index was as low as 1%." (PMID 31391089, 2019). "Tumour cells were immunoreactive for CD99 but negative for epithelial membrane antigen and progesterone receptor." (PMID 30819134, 2019). "No apparent increase was observed in expression of CD99 or CD73 upon co-culture of the tumor cells and fibroblasts." (PMID 31510956, 2019). "Inhibiting the overexpressed CD99 may improve resectability and decrease the recurrence rate of GBM by decreasing tumor cells migration and invasion." (PMID 30845661, 2019). "In the current case, the tumor was negative for neuroendocrine markers, lymphocyte markers and muscle markers and diffusely positive for CD99, so the patient was diagnosed initially with ESFT." (PMID 30453921, 2018). "Incisional biopsy of the gingival lesion displayed diffuse infiltration of undifferentiated tumor cells with granulocytic appearance, strongly immunopositive for CD99, myeloperoxidase and Ki-67 (60%), and negative for CD20, CD3, CD34 and TdT." (PMID 29075423, 2017). "Because the tumor cells were positive for CD99 and BCL-2, which are usually negative in a case of malignant mesothelioma, malignant sarcomatoid mesothelioma seemed to be less of a possibility." (PMID 28205183, 2017). "Tumor cells were commonly positive for TDT (21/26, 80.8%), CD3 (29/31, 93.5%), and CD7 (25/27, 92.6%), and they were variably positive for CD5 (16/24, 66.7%), CD99 (14/19, 73.7%), CD2 (12/18, 66.7%), and CD1a (13/21, 61.9%)." (PMID 28566711, 2017). "In particular, CXCR4 negative/CD99 positive tumor cells were present in abundance in tumors that arose from CXCR4 positive cells." (PMID 27528222, 2016).
tumor (continued). "Two major issues of the correct diagnostic orientation are the recognition of a possible non-lymphoid CD45 positivity and ruling-out of the aberrant CD99 antigen from the pivotal markers in this tumour type." (PMID 27019694, 2016). "The tumor cells were positive for CD99, FLI1 and EMA, but negative for CD3, CgA, CD20, CKpan, S100 and HMB45." (PMID 25780425, 2015). "IHC revealed that the tumor diffusely expressed CD34, CD99, Bcl2, PAX8, NAB2, STAT6, and GRIA2." (PMID 26337721, 2015). "Furthermore, the ectopic expression of the EWSR1 fusion in mouse MSC led to tumor development with overlapping features with EWS, namely CD99 overexpression." (PMID 24498265, 2014). "The tumor cells were positive for CD99 and neuron specific enolase, negative for cytokeratin, leukocyte common antigen and myogenin." (PMID 25404964, 2014). "The tumor cells were positive for tumor cell glial fibrillary acidic protein (GFAP), S-100 protein, vimentin, human leukocyte differentiation antigen 34 (CD34), epithelial membrane antigen (EMA), cluster of differentiation 99 (CD99) and D2-40." (PMID 24348765, 2014). "On immunohistochemical staining, the tumor cells were positive for vimentin and CD99, but negative for alpha smooth muscle actin, desmin, and S-100 protein." (PMID 24969223, 2014). "Immunohistochemistry has shown that non-adipocytic tumor cells are consistently positive for CD99 and, less frequently, for CD34 (75%) and Bcl-2 (60%)." (PMID 24179528, 2013). "Immunohistochemically, the tumor cells were strong positive for CD56, CD3ε, TIA1, and weak positive for LMP1, and negative for CD5, CD8, CD20, CD79a, CgA, Syn, SCLC, CK, EMA, CD99, CD10, TdT, PAX-5, and BCL-6." (PMID 23958352, 2013). "When evaluated by immunohistochemistry, the tumor tissue expressed mesenchymal cell makers Vim, CK, and CD99, neural cell markers NF and NES, but was negative for epithelial markers EMA and Des." (PMID 24339974, 2013). "All 3 had strong tumor nuclear BAF47 staining and all expressed bcl2 and CD99." (PMID 24131748, 2013). "Ash and colleagues have recently reported an alternative flow cytometry method which identifies tumor cells expressing both CD99 and CD90 but which are negative for a hematopoietic panel including CD45, CD3, CD14, CD16, and CD19." (PMID 22550426, 2012). "In this case, both the pathologic characteristic and the positive expression of CD99, S-100 and NSE in the tumor cells could support the diagnosis of rPNET." (PMID 23270507, 2012). "Immunohistochemically, the tumor cells were strongly positive for bcl-2 and CD99, partly positive for CK and EMA, and negative for CD117, CD34, SMA and desmin in all five cases." (PMID 22862905, 2012). "Furthermore, the tumor cells stained positive for CD2, CD3, CD7, CD99, Perforin and, remarkably, CD8." (PMID 22497840, 2012). "Although there is no current known ligand for CD99, in vitro studies on ES cell lines have demonstrated that CD99 binding and silencing by specific antibodies induces rapid tumor cell death." (PMID 21151650, 2011). "However, other pathways are operative in this patient's tumor, including Ras/Raf /ERK and STAT3.The relative overexpression of CD99 in this patient is consistent with activation of this pathway (not shown)." (PMID 21494688, 2011). "The tumor cells expressed CD99 (MIC2 gene), NSE and S100 protein, but were non-reactive to cytokeratins, epithelial membrane antigen, desmin, smooth muscle actin, chromogranin and leucocyte common antigen." (PMID 19830128, 2009). "Immunohistochemistry showed benign epithelial positivity for cytokeratin and focal malignant stromal positivity for smooth muscle actin and CD10; however, the tumor was negative for CD99, Wilm's tumor protein, SS18-SSX, BCOR, and estrogen/progesterone receptors." (PMID 41681728, 2026).
tumor (continued). "We identified RCC-specific features including enhanced T cell exhaustion, pro-angiogenic and immunosuppressive MC polarization, and a malignant CASC15+KLK6+ epithelial subpopulation that may drive tumor progression through MIF and CD99-mediated intercellular communication." (PMID 40932351, 2026). "The tumor cells were positive for CD99 and vimentin but negative for CK and CD45." (PMID 40060231, 2025). "In our case, the tumor was positive for vimentin and CD99 and negative for CK, NSE, and CD45." (PMID 40060231, 2025). "Similarly, CD99 represents a crucial target for identifying and isolating circulating tumor cells (CTCs), thereby aiding in the detection of potential micro metastases during the follow-up of EWS patients in the late stages of tumor progression." (PMID 40427525, 2025). "CD99 was positive in one tumor, while LIN28A was absent in all." (PMID 40751809, 2025). "Tumor cells of another case are negative for CD99, WT-1, S100, synaptophysin, and chromogranin." (PMID 38854270, 2024). "The tumor cells do not express Bcl-2, CD99, or CD34, which is beneficial for differentiation." (PMID 39206171, 2024). "Tumor cells of thoracopulmonary PNETs are CD99-positive but cytokeratin-negative." (PMID 35354472, 2022). "Besides tumour cells, CD99 antigen is also expressed on the surface of leukocytes population (CD45+), thus for the analysis of β3-Ars expression on EWS tumour cells it was necessary to evidence the CD45+ population to deplete it and enrich for CD45− CD99+ tumour cells." (PMID 33066095, 2020). "During the experimental period of 14 weeks of the tumor growth study we did not observe any toxicity of the TRXtr-mCD99 vaccine as addressed by body weight or macroscopic and behavioral characteristics between CD99 vaccinated and control-vaccinated mice." (PMID 31001265, 2019). "A full appreciation of how the presence or absence of CD99 may affect tumor infiltration and the cross-talk between tumor and normal host cells may open new therapeutic avenues." (PMID 29534016, 2018). "CD99 engagement induces death in tumor cells via non-conventional, caspase-independent programmed cell death or through a non-apoptotic pathway resembling methuosis, a process characterized by excessive accumulation of vacuoles in the cytoplasm, leading to compromised cell viability." (PMID 29305692, 2018). "The lack of CD34 and CD99 expression in our case can also help to exclude this tumor." (PMID 23227905, 2012). "The tumor cells were positive for CD99 and negative for chromogranin A, keratin and desmin." (PMID 21494688, 2011). "However, a role for tumour cell CD99 in TEM and metastasis is not well defined." (PMID 34374417, 2021). "The downregulation of this pathway through CD99 knockout, may enable the regulation of the migration and invasion of GBM cells, particularly in the mesenchymal subtype, and may increase the clinical outcome, thereby improving tumor resectability and decreasing the tumor recurrence rate." (PMID 30845661, 2019). "The immunohistochemical examination showed that the tumor cells were positive for CD34 and CD99 while negative for smooth muscle Actin, Desmin, and S100." (PMID 40709355, 2025). "In our case, the tumor cells were positive for CD34 and CD99 while negative for smooth muscle Actin, Desmin and S100." (PMID 40709355, 2025). "The tumor diffusely expressed NUTM1, was positive for WT1cter at weak to moderate intensity, and was focally positive for CD99, while it was negative for keratins, EMA, P40, MyoD1, myogenin, NKX2.2, BCOR, and pan-TRK." (PMID 38851744, 2024). "Among these, the expression of STAT6 in the tumor cell is essential for diagnosis when CD34 and CD99 are negative." (PMID 39574987, 2024). "The interactions where non-tumor cells influenced tumor cells included NAMPT → INSR, MIF → CD74 and CXCR4, GRN → SORT1, and CD99 → CD99." (PMID 39095793, 2024).
tumor (continued). "The tumor cells expressed SATB2, Bcl-2, TLE1, SMARCB1, but not CK, EMA, CD34, SMA, Desmin, S-100, CD99, STAT6, MyoD1, Myogenin, and Ki-67 LI is about 10%." (PMID 37361584, 2023). "Tumor cells are typically positive for α-inhibin, calretinin, SF1, Melan-A, CD56 and CD99, and negative for EMA and occasional expression of other keratin markers." (PMID 37518334, 2023). "The tumor cells were negative for AE1/3, Cam5.2, CKIT, DOG1, CD99, SOX10, S100, HMB45, MelanA, Syn, CgA, Trypsin, Desmin, SMA, Caldesmon, collagen type 4, Laminin, Inhibin, Calretinin, STAT6, CD34, ERG, WT1, ER, PR, and SALL4." (PMID 36928336, 2023). "Immunohistochemical staining of diagnostic markers showed expression of EMA, vimentin, NSE and CD99, and absence of AFP, which is comparable to the results in the primary tumor." (PMID 38201285, 2023). "To verify cell apoptosis due to CD99 CAR T-ALL cells recognizing and attacking CD99+ tumor cells, not due to the negative effect of virus transfection, we constructed a CD99-knock-down cell line, which was named shCD99 MOLT-4." (PMID 37112766, 2023). "The tumor cells showed immunopositivity for CD34, STAT-6, and no expression of CD99, AML, S-100, and Ki-67." (PMID 36426115, 2022). "Tumor cells were positive for pan-cytokeratin (Pan CK), synaptophysin, vimentin, and S100 (focal) and negative for CD45, CD99, and desmin." (PMID 36259025, 2022). "In our case, the tumor presented with strongly positive STAT6 and CD34, moderately positive CD99, negative EMA and S-100 markers, mitoses <5/10 HPF, and absence of necrosis, suggesting the diagnosis of grade 1 SFT." (PMID 36060387, 2022). "Tumor cells showed immunopositivity for CD34 and STAT-6 and no expression of CD99, AML, S-100, and Ki-67." (PMID 36426115, 2022). "Immunofluorescence of PuMA lung sections from A673 EwS cells revealed the presence of Granzyme B in proximity to CD99-positive cells in NOD-SCID mice, but not NSG mice, at day 3 following tumor cell injection." (PMID 33828989, 2021). "The tumor cells were positive for Trk and SMA, but negative for S100, CD34, ALK, CD10, desmin, myogenin, CD99, CD56, CK, EMA, and STAT6." (PMID 32957984, 2020). "For non-EwS cases, the proposed marker combination of CD99, BCL11B, and GLG1 yielded a consistent classification over all 3 cores taken from different areas of each tumor sample in 95.2%." (PMID 32164354, 2020). "Immunohistochemistry showed that the tumor cells were positive for WT1 (strong and diffuse nuclear and cytoplasmic), caldesmon, CD99 (cytoplasmic, not membranous), S100 (subset), and SMA (subset)." (PMID 32490123, 2020). "Immunohistochemical staining is required for the diagnosis of SFTP; the tumor cells are positive for STAT6, CD34, CD99, and BCL2, whereas they are negative for desmin, S-100, and alpha-SMA." (PMID 32638177, 2020). "Immunohistochemical analysis revealed tumor cells were positivity for Bcl2, CD5, and p40, while infiltrated lymphocytes were positive for CD3 and negative for CD99." (PMID 31655916, 2019). "In this study, we thoroughly investigate the capability of EXOs lacking CD99 (CD99neg EXOs), released from CD99-silenced EWS cells, to interfere with the aggressive profile of tumor cells." (PMID 31209202, 2019). "Immunohistochemically tumor cells were positive for Bcl2 and Cytokeratin AE1 + AE3, while infiltrated lymphocytes were positive for CD3 and CD5 and negative for CD99." (PMID 31655916, 2019). "Based on immunohistochemical examination, the tumour cells were positive for CD34, Bcl2, vimentin, and CD99 and negative for desmin and S-100." (PMID 31391089, 2019). "Tumor cells exhibit no strong diffuse staining for CD34 and are basically negative for AE1/AE3, Bcl-2, CD34, CD99, CD117, Factor VIIIR Ag, S-100 protein, and STAT6." (PMID 30206803, 2019). "On immunohistochemistry, the tumor was positive for CD34 and CD99 and negative for α-SMA, S-100, and bcl-2." (PMID 28326216, 2017).